PNN (pinin, desmosome associated protein)
Description:
Transcriptional activator binding to the E-box 1 core sequence of the E-cadherin promoter gene; the core-binding sequence is 5'CAGGTG-3'. Capable of reversing CTBP1-mediated transcription repression. Auxiliary component of the splicing-dependent multiprotein exon junction complex (EJC) deposited at splice junction on mRNAs. The EJC is a dynamic structure consisting of core proteins and several peripheral nuclear and cytoplasmic associated factors that join the complex only transiently either during EJC assembly or during subsequent mRNA metabolism. Participates in the regulation of alternative pre-mRNA splicing. Associates to spliced mRNA within 60 nt upstream of the 5'-splice sites. Component of the PSAP complex which binds RNA in a sequence-independent manner and is proposed to be recruited to the EJC prior to or during the splicing process and to regulate specific excision of introns in specific transcription subsets. Involved in the establishment and maintenance of epithelia cell-cell adhesion. Potential tumor suppressor for renal cell carcinoma.
Synonyms: DRSP; DRS; MEMA; SDK3
Tractability: Antibody: its Gene Ontology location is reachable by antibodies, with high confidence. PROTAC: UniProt records ubiquitination sites on it; ubiquitination databases record sites on it; its protein half-life has been measured.
Gene: Protein-coding gene on chromosome 14 (39,175,163 to 39,183,220, forward strand). Ensembl gene ENSG00000100941.
Subcellular location: Nucleus speckle; Cell junction, desmosome
Subcellular location (Human Protein Atlas): Nuclear speckles
Pathways (Reactome):
Metabolism of RNA: mRNA Splicing - Major Pathway
Gene Ontology:
Molecular function: protein binding; RNA binding; structural molecule activity
Biological process: cell adhesion; mRNA splicing, via spliceosome; mRNA stabilization; positive regulation of apoptotic process; regulation of mRNA processing
Cellular component: catalytic step 2 spliceosome; exon-exon junction complex; membrane; nuclear speck; nucleus; cell-cell junction; intermediate filament; nucleoplasm; plasma membrane; desmosome
Genetic constraint (gnomAD): Loss-of-function variants: 24 observed, 59.8 expected, observed/expected ratio (o/e) 0.4, 90% interval 0.29 to 0.56. The upper end of that interval is the gene's LOEUF score, 0.56, which puts it in group 2 of 6, group 1 being the genes least tolerant of losing a copy. Missense variants: 741 observed, 770.06 expected, observed/expected ratio (o/e) 0.96, 90% interval 0.9 to 1.02. Synonymous variants: 296 observed, 246.63 expected, observed/expected ratio (o/e) 1.2, 90% interval 1.09 to 1.32.
Homologues: Orthologues: chimpanzee PNN (99% identical), macaque PNN (99% identical), dog PNN (95% identical), pig PNN (95% identical), guinea pig PNN (94% identical), rabbit PNN (94% identical), mouse Pnn (94% identical), rat Pnn (93% identical), tropical clawed frog pnn (64% identical), zebrafish pnn (55% identical), Caenorhabditis elegans pnn-1 (16% identical), Drosophila melanogaster Pnn (13% identical).
Diseases named in the same sentence as PNN in open-access papers:
PNN is named in the same sentence as 22 diseases in open-access papers, as found by Europe PMC text mining. Sharing a sentence is not in itself a finding about the gene and the disease. The quoted sentences say what the papers report.
nasopharyngeal carcinoma (3 papers, 2020 to 2024). A carcinoma arising from the nasopharyngeal epithelium. "In nasopharyngeal carcinoma (NPC), lncRNA AATBC was significantly expressed and upregulated desmosome-associated protein pinin (PNN) expression by miR-1237-3p sponging." (PMID 39313797, 2024). "However, recent studies have demonstrated that PNN was overexpressed in several types of cancer, including hepatocellular carcinoma (HCC), colorectal cancer (CRC), ovarian cancer and nasopharyngeal carcinoma, and acted as an oncogenic factor, contributing to disease progression and poor survival." (PMID 33811436, 2021).
renal cell carcinoma (3 papers, 2016 to 2023). "PNN was previously supposed as a tumor suppressor (e.g. in renal cell carcinomas) by analysis of genetic location and methylation of CpG islands." (PMID 27107420, 2016). "Additionally, PNN exhibits a dichotomous function in cancer biology by promoting cell proliferation and impeding apoptosis in liver cancer, while concurrently facilitating carcinogenic processes in renal cell carcinoma by curtailing apoptosis and enhancing cell migration and invasion." (PMID 37814309, 2023).
colon adenocarcinoma (2 papers, 2023 to 2026). "In addition, elevated expression of pinin (PNN) has been observed in colon adenocarcinoma, contributing to enhanced glycolysis in cancer cells and subsequently facilitating their proliferation, migration, and invasiveness." (PMID 41517663, 2026). "Notably, heightened PNN expression levels have been documented in gastrointestinal neoplasms, rendering it a viable independent prognostic indicator and immunotherapeutic response predictor in colon adenocarcinoma (COAD)." (PMID 37814309, 2023).
melanoma (2 papers, 2018 to 2021). A malignant, usually aggressive tumor composed of atypical, neoplastic melanocytes. "Further investigation of the potential role of PNN as a tumour suppressor showed low PNN expression in cancer‐derived tissues and cancer cell lines, including epithelial‐derived RCC cell lines, B‐cell lymphoma cell line, and melanoma cell line." (PMID 33811436, 2021).
ovarian carcinoma (2 papers, 2021). A malignant neoplasm originating from the surface ovarian epithelium. "Furthermore, HNRNPC, CRNKL1, PNN and PPIE were also reported to have a high expression and biological function in several cancers including ovarian cancer 21-24." (PMID 33437214, 2021).
colon cancer (1 paper, 2024). "Here, using a public data repository, we found that PNN expression was overexpressed in colon cancer tissues compared to normal adjacent mucosa at both the mRNA and protein levels." (PMID 38892168, 2024). "Using a public data repository, we found that PNN was a negative prognostic factor and was overexpressed in colon cancer tissues from stage 1 of the disease." (PMID 38892168, 2024).
leiomyoma (1 paper, 2007). A well-circumscribed benign smooth muscle neoplasm characterized by the presence of spindle cells with cigar-shaped nuclei, interlacing fascicles, and a whorled pattern. "They included several genes such as NR2F1, PNN, Smad4, Smad5, STAT5B, JUN, TGIF2, and ATF1 that were over-expressed while RUNX3, STAT1, STAT6, EGR3, GAS7, Smad1, and EDF1 were underexpressed in leiomyomas as compared to keloid/incisional scars." (PMID 17718906, 2007).
lung carcinoma (1 paper, 2024). "Since miR-1237-3p is expressed in lung cancer, therefore, lncRNA AATBC may function as ceRNA of PNN gene by competitively interacting with miR-1237-3p and eventually increasing lung cancer via miR-1237-3p/PNN/ZEB axis." (PMID 39313797, 2024).
osteosarcoma (1 paper, 2023). A usually aggressive malignant bone-forming mesenchymal neoplasm, predominantly affecting adolescents and young adults. "Furthermore, the interaction between hsa-circ-0032463 and PNN assumes significance in the realm of osteosarcoma (OS), with hsa-circ-0032463 acting as a potent promoter of tumorigenesis via regulation of the miR-330-3p/PNN axis." (PMID 37814309, 2023).
prostate carcinoma (1 paper, 2023). A carcinoma that arises from epithelial cells of the prostate gland. "Furthermore, the PNN gene features prominently in the spliceosome-associated pathways of prostate cancer (PCa) and has been identified as a potential diagnostic marker for PCa." (PMID 37814309, 2023).
cancer (10 papers, 2016 to 2026). A tumor composed of atypical neoplastic, often pleomorphic cells that invade other tissues. "Based on the specific function of PNN in cell‐cell adhesion and alternative RNA splicing, PNN was expected to have a regulatory effect on cancer progression." (PMID 33811436, 2021). "Given the inconsistency in PNN expression and function in cancers reported by previous studies, we aimed to investigate the subcellular localization and expression of PNN in RCC samples in the present study." (PMID 33811436, 2021). "The result indicated that high PNN expression was significantly related to several signalling pathways, which were believed to be involved in cancer progression, including JAK/STAT, MAPK, Notch, T cell receptor, VEGF and WNT signalling pathways." (PMID 33811436, 2021). "The abnormal expression of PNN in several cancers could be explained by aberrant methylation of CpG islands in PNN promoter region." (PMID 33811436, 2021). "In order to assess whether PNN was deregulated in CRC patients, we performed a bioinformatic analysis exploiting the UALCAN tool, a web resource for analyzing cancer OMICS data from TCGA." (PMID 38892168, 2024).
tumor (7 papers, 2016 to 2024). "As a consequence, an alteration in desmosome composition or components was associated with tumor progression and the deregulation of PNN was related to embryonic development, cellular differentiation, tumorigenesis, and metastasis." (PMID 38892168, 2024). "In contrast, recent studies have shown that PNN was overexpressed in tumours and was associated with tumour progression and poor prognosis." (PMID 33811436, 2021). "In the present study, we aimed to investigate the prognostic role of PNN in RCC and the underlying molecular mechanisms by which PNN regulates tumour progression." (PMID 33811436, 2021). "Therefore, we suggest the regulation of tumour immune microenvironment as an underlying mechanism by which PNN promotes tumour progression in RCC." (PMID 33811436, 2021). "In this view, according to its function of intercellular adhesion reinforcement, it seems that desmosome‐associated molecules, such as PNN, might be considered as tumour invasion suppressors." (PMID 33811436, 2021). "Moreover, overexpression of PNN was significantly associated with an aggressive tumor phenotype and a poor prognosis according to our study and the results of GEO database." (PMID 27107420, 2016). "Then, we assessed PNN expression in CRC tissue specimens, confirming the overexpression of PNN in tumor sections." (PMID 38892168, 2024). "In Luminal B BRCA, PNN was the only gene that passed the significant threshold (log FC > 0.5, p < 0.01) and was downregulated in tumor samples." (PMID 34630526, 2021). "Interestingly, the deregulation of PNN was related to CRC tumor progression in vitro and in vivo, activating the EGFR/ERK pathway." (PMID 38892168, 2024). "Additionally, the expression and subcellular localization of PNN were found to be altered in various primary tumour tissues." (PMID 33811436, 2021). "In Basal-like BRCA, PUF60 was upregulated and PNN was downregulated in tumor samples." (PMID 34630526, 2021). "Moreover, results of IHC analyses revealed that PNN was overexpressed in tumor tissue and metastasis lymph node compared to the adjuvant tissue and normal mucosa." (PMID 27107420, 2016). "Recently, studies indicated that different localizations of PNN, like β-catenin, might play diverse roles in tissue remodeling and tumor progression." (PMID 27107420, 2016). "Furthermore, the potential role of PNN as a tumor suppressor was presented based on its genetic locus and methylated CpG islands." (PMID 27107420, 2016). "Besides, we selected 5 key genes (SRSF2, HELLS, PNN, TK1, and CKS2) in hallmark_E2F_targets in Pathcards database and validated that they are associated with overall survival, metastasis, and tumor stage of patients with PCa through multiple online database validation." (PMID 35392496, 2022). "Similarly, these results indicated that the PNN gene could be a useful prognosis feature for PCa patients in clinical practice related to tumour progression and poor prognosis." (PMID 36468018, 2022). "We further analyzed PNN expression in CRC and other tumor tissues based on GEO database." (PMID 27107420, 2016).
infection (3 papers, 2020 to 2024). The state of being infected such as from the introduction of a foreign agent such as serum, vaccine, antigenic substance or organism. "Cell growth and differentiation (HRASLS2), transport (PNN, SLC4A4, and HBA1), metabolism (SRD5A3), and immune response (SSC4D) involved genes were highly regulated in the early HEV gt3 infection." (PMID 32877413, 2020).
immune disorders (1 paper, 2024). "Additionally, phagosomes were implicated in certain immune disorders, with RPS4Y1, RPS10, SRRM1, and PNN target genes playing roles in the NOD-like receptor signaling pathway." (PMID 38770048, 2024).
neurodegenerative disease (1 paper, 2023). A disorder of the central nervous system characterized by gradual and progressive loss of neural tissue and neurologic function. "Tau aggregates are a hallmark of multiple neurodegenerative diseases and can contain RNAs and RNA-binding proteins, including serine/arginine repetitive matrix protein 2 (SRRM2) and pinin (PNN)." (PMID 36626563, 2023).
neurodevelopmental disorder (1 paper, 2023). A behavioral and cognitive disorder with onset during the developmental period that involves impaired or aberrant development of intellectual, motor, or social functions. "In addition to SRRM2 and PNN, we tested SETD1A—a histone methyltransferase implicated in neurodevelopmental disorders that contains 24 consecutive serines—and observed enrichment in tau aggregates." (PMID 36626563, 2023).
PNN also shares sentences with these, for which no sentence is quoted: ankylosis (1 paper); B‐cell lymphoma (1); colorectal cancer (1); gastrointestinal neoplasms (1); hepatocellular carcinoma (1); liver cancer (1).